LYZ (lysozyme)
Diseases named in the same sentence as LYZ in open-access papers (continued):
Sharing a sentence is not in itself a finding about the gene and the disease.
sarcoidosis (continued). "Elevated levels of serum lysozyme have been reported in granulomatous uveitis especially sarcoidosis and tuberculosis." (PMID 26879979, 2016). "The levels of at least one of the serum markers ACE and lysozyme were found elevated in 58 % of patients with biopsy-proven sarcoidosis." (PMID 26879979, 2016). "Pairwise comparisons of the serum lysozyme levels between patients with presumed sarcoidosis and AS and BD revealed statistically significant differences for presumed sarcoidosis (p = 0.0001 and p = 0.0001 respectively)." (PMID 26879979, 2016). "The sensitivity of serum lysozyme for predicting sarcoidosis was reported as 79.1 % and the sensitivity of serum ACE for predicting sarcoidosis was reported as 59 %." (PMID 26879979, 2016). "An initial work-up for sarcoidosis (lysozyme, angiotensin-converting enzyme, chest X-ray), syphilis (Treponema pallidum Ab, RPR), and tuberculosis (QuantiFERON®-TB Gold) was negative." (PMID 27421273, 2016). "Increased serum levels of angiotensin converting enzyme and lysozyme are considered as inflammatory markers for diagnosis of sarcoidosis which is an autoimmune inflammatory disease." (PMID 26879979, 2016). "Although the sensitivity of serum lysozyme in sarcoidosis is low, some studies have suggested that it may be suitable for prognostic evaluation." (PMID 40502903, 2025). "1-α hydroxylase in these cells could lead to hypercalcemia and positivity of lysozyme might contribute to a supporting finding for the diagnosis of sarcoidosis in the future." (PMID 38890580, 2024). "Since lysozyme was also produced from infiltrating macrophages into the affected tissue of sarcoidosis same as 1-α hydroxylase, the positivity of lysozyme staining could potentially serve as a novel supportive finding for the diagnosis of sarcoidosis." (PMID 38890580, 2024). "Absence of pulmonary symptoms, normal ophthalmologic examination, normal serum angiotensin-converting enzyme (ACE), lysozyme, and 25 (OH) vitamin D levels, as well as histopathologic examination substantiated the exclusion of sarcoidosis as a prima facie diagnosis in our patient." (PMID 35382864, 2022). "ACE and lysozyme have been traditionally used as diagnostic markers for sarcoidosis, but their sensitivities are not satisfactory, ranging from 29% to 63% for ACE and from 26% to 79% for lysozyme." (PMID 35663496, 2022). "The proportion of elevated serum ACE versus lysozyme was compared in the sarcoidosis patients." (PMID 33805490, 2021). "In addition, sIL2R is more sensitive than serum ACE and lysozyme levels for a diagnosis of sarcoidosis, although sIL-2R levels can also be elevated in hematologic malignancy, autoimmune disorders and idiopathic pulmonary fibrosis." (PMID 34573900, 2021). "It showed higher sensitivity and specificity than other biomarkers, including angiotensin converting enzyme (ACE), lysozyme and soluble IL-2 receptor and it has been found increased in active sarcoidosis patients showing to predict clinical course, steroid responsiveness and relapse of the disease." (PMID 31906975, 2020). "Sarcoidosis patients show increased concentration of lysozyme at onset." (PMID 30944672, 2019). "The mean (SD) differences of serum lysozyme levels between patients with presumed sarcoidosis and AS, BD, presumed latent TB, presumed latent syphilis and control group were 6.641 (1.334), 6.394 (1.346), 5.778 (1.392), 6.785 (2.198), and 7.568 (1.756) mg/L respectively." (PMID 26879979, 2016). "The increase in serum lysozyme level was significant for patients with presumed sarcoidosis with respect to ankylosing spondylitis (p = 0.0001), behcet’s disease, (p = 0.0001) presumed latent tuberculosis (p = 0.001), presumed latent syphilis (p = 0.033), and control group (p = 0.0001)." (PMID 26879979, 2016).
sarcoidosis (continued). "The mean (SD) values of serum lysozyme level for patients with AS, BD, presumed sarcoidosis, presumed latent TB, presumed latent syphilis and control group were 14.096 (4.586), 14.244 (5.358), 20.712 (6.780), 15.259 (8.516), 14.018 (6.679) and 12.927 (4.720) mg/L respectively." (PMID 26879979, 2016). "This study compares for the first time the serum ACE and lysozyme levels of patients diagnosed with ocular involvement of autoimmune diseases such as AS, BD and presumed sarcoidosis and ocular involvement of infectious diseases such as presumed latent TB and presumed latent syphilis." (PMID 26879979, 2016). "Lysozyme is another marker of disease activity that, when elevated, might suggest a diagnosis of sarcoidosis." (PMID 24987524, 2014). "One retrospective review of patients with biopsy-proven sarcoidosis and uveitis suggested that although the sensitivities of ACE and lysozyme are low in isolation, when both tests are used in combination with chest X-ray, over 80% of patients had at least one marker suggestive of sarcoidosis." (PMID 24987524, 2014). "In one Japanese study, lysozyme had a sensitivity of 79% for predicting sarcoidosis." (PMID 22937766, 2012). "Although clinical laboratory testing of serum angiotensin-converting enzyme (ACE), lysozyme, neopterin, and soluble interleukin 2 receptor (sIL-2R), which are produced by activated T cells or macrophages, is used as a diagnostic marker for sarcoidosis, their diagnostic ability is not satisfactory." (PMID 35663496, 2022). "In addition, serum lysozyme can be used as a marker for sarcoidosis." (PMID 22937766, 2012). "Serum eHSP90α level in sarcoidosis patients was significantly correlated with several biomarkers of sarcoidosis, including ACE, sIL-2R, and lysozyme." (PMID 39881845, 2025). "In sarcoidosis granuloma samples, the expression of genes such as ACE and lysozyme (LYZ) is known to be elevated, and these genes were indeed upregulated in TREM2 macrophages." (PMID 38038136, 2023). "The group with proven sarcoidosis (n = 17) presented an ACE level of 46.69 ± 23 IU/L and a lysozyme level of 43± 67 mg/L." (PMID 33805490, 2021). "More recently, a soluble form of the IL-2 receptor (sIL-2R) which is secreted by T-cells upon activation, has shown promise as a more sensitive and specific marker for sarcoidosis compared to traditional tests such as ACE and lysozyme." (PMID 33036432, 2020). "While increased CTO is not specific for sarcoidosis, the enzyme has proven to be a very sensitive biomarker of active sarcoidosis and has more sensitivity and specificity than other commonly used sarcoid biomarkers such as ACE and lysozyme." (PMID 33036432, 2020). "Serum tests that show promise for detection of sarcoidosis include serum CTO and sIL-2R which have higher sensitivity and specificity than the more commonly used sarcoid biomarkers ACE and lysozyme." (PMID 33036432, 2020). "Traditionally used markers of sarcoidosis such as Angiotensin Converting Enzyme (ACE) and lysozyme—enzymes produced by granuloma macrophages—display low sensitivity and/or specificity." (PMID 33036432, 2020). "In sarcoidosis patients, chitotriosidase showed higher sensitivity and specificity than other biomarkers, including angiotensin converting enzyme (ACE), lysozyme and soluble IL-2 receptor." (PMID 31906975, 2020). "Positive correlations were detected among sarcoidosis biomarkers, including ACE, lysozyme, chitotriosidase, and KL-6 that can therefore be included in the list of prognostic indicators." (PMID 30944672, 2019). "Members of the international Workshop on Ocular Sarcoidosis recommended elevated serum angiotensin converting enzyme (ACE), elevated serum lysozyme and abnormal liver enzyme tests." (PMID 26799486, 2016). "Laboratory markers, like lysozyme and soluble interleukin 2, were not routine examinations for the patients with sarcoidosis in our clinical setting." (PMID 29785303, 2018).
sarcoidosis (continued). "In our study, the sensitivity of NSE alone seems comparable to those of the traditional markers ACE and lysozyme, but its combinations with ACE and sIL-2R resulted in a greater sensitivity, providing the additional value of NSE in combination with such traditional markers for sarcoidosis." (PMID 35663496, 2022). "Although the typical concentration of lysozyme in serum is 2.8 ± 0.8 mg/L, its concentration in body fluids rises on the onset of several diseases such as AIDS, cancer, malaria, Alzheimer’s disease, meningitis, rheumatoid arthritis, sarcoidosis, and Crohn’s disease." (PMID 32050422, 2020). "Other markers ofmacrophage activation, such as lysozyme, neopterin, serum amyloid A,chitotriosidase may also be elevated in patients with active sarcoidosis andmight be used to assess disease activity rather than as diagnostic markers, dueto their low specificity." (PMID 39077350, 2024).
COVID-19 (21 papers, 2021 to 2025). A disease caused by infection with severe acute respiratory syndrome coronavirus 2. "It is hypothesized that the natural proteins lactoferrin, ovotransferrin, and lysozyme, which are abundant in nature and have wide-ranging antiviral as well as immunomodulatory properties, may mitigate COVID-19-associated pathology." (PMID 37621850, 2023). "An inverse correlation was found between ferritin and lysozyme in serum (p < 0.05), suggesting that iron could have impaired an important innate immune system anti-viral effector and could partially explain future COVID-19 susceptibility." (PMID 37108697, 2023). "This has led to lysozyme being included among antimicrobial peptides with potential applications in COVID-19 therapy." (PMID 41306594, 2025). "PIRV-F20® (Farmagens Health Care s.r.l., Naples, Italy), a multicomponent supplement with vitamins, trace elements, probiotics, lactoferrin, lysozyme, and resveratrol, was tested in 44 long COVID-19 patients with reduced exercise capacity." (PMID 40507071, 2025). "Recently, the potential therapeutic use of lysozyme as antiviral and immune-modulating agent against COVID-19 was proposed." (PMID 36985820, 2023). "Lysozyme is also known to have neuroprotective functions which can be effective to prevent neurological COVID-19 outcomes." (PMID 36424926, 2022). "Considering the ease of the oral administration of lysozyme, also in combination with other therapies, if these data are confirmed by a more detailed analysis, it could be hypothesized that lysozyme could also be used to mitigate the manifestation of COVID-19." (PMID 38338396, 2024). "Natural proteins found in milk (lactoferrin) and egg white (ovotransferrin and lysozyme) could have therapeutic value in COVID-19 through their effects on the immune system." (PMID 37621850, 2023). "Importantly, prior studies have shown that lysozyme can play a role in antiviral activity and suggest that low lysozyme levels (as found in COVID-19) may increase virulence." (PMID 34966385, 2021). "The aim of the current report is to evaluate the effects of a combination of lactoferrin, lysozyme, lactobacillus, resveratrol, vitamins, and oligoelements (PIRV-F20®) on the exercise capacity of post-COVID-19 patients." (PMID 39124710, 2024). "Increased levels of S100A8, MKI67, HSPA5, LYZ, CTSD, and IGHG1 were observed in COVID-19 patients." (PMID 39026676, 2024). "Although the interaction between lysozyme and SARS-CoV-2 has not been studied, lysozyme aerosol treatment is known to be effective in decreasing inflammation, which could help against COVID-19-related lung complications." (PMID 36424926, 2022). "Notably, in severe/critical COVID-19 patients in the recovery stage, the proportion of CD14 monocytes (based on the expression of the marker genes CST3, LYZ, CD14) in PBMCs were elevated, but CD4 T cells (IL7R, LTB) were decreased, consistent with a previous report." (PMID 35046942, 2021).
systemic amyloidosis (19 papers, 2005 to 2025). "The effect of lysozyme susceptibility to amyloid formation is the occurrence of a disease known as “familial or systemic amyloidosis,” characterized by the formation of lysozyme amyloid deposits in the kidneys, liver, and spleen." (PMID 41373463, 2025). "Mutational variants of human lysozyme cause fatal systemic amyloidosis by depositing kilograms of protein in the viscera of patients." (PMID 40557600, 2025). "Mutational variants of human lysozyme cause a rare but fatal hereditary systemic amyloidosis by populating an intermediate state that self‐assembles into amyloid fibrils." (PMID 40557600, 2025). "Hen’s egg-white lysozyme is widely used as a food additive and has close homology to human lysozyme, which is then associated to heritable systemic amyloidosis if it is further mutated." (PMID 32311316, 2020). "Populating transient and partially unfolded species is a crucial step in the formation and accumulation of amyloid fibrils formed from pathogenic variants of human lysozyme linked with a rare but fatal hereditary systemic amyloidosis." (PMID 29101328, 2017). "Systemic amyloidosis is a lysozyme-associated disease caused by the deposition of lysozyme in the amyloid fibril form in spleen, kidney, and liver cells." (PMID 27768744, 2016). "Lysozyme, an antibacterial protein, is a well-studied model since it is associated in human with systemic amyloidosis and that is widely available from chicken eggs (HEWL, hen egg white lysozyme)." (PMID 27512096, 2016). "Human lysozyme is a structural homologue of HEWL, which is known to be involved in a systemic amyloidosis disease due to a point mutation in the lysozyme gene." (PMID 24066139, 2013). "In the case of lysozyme, the aggregation of which is involved in hereditary systemic amyloidosis, single point mutations in the lysozyme gene are associated with fibril deposition in several tissues." (PMID 17588526, 2008). "In the case of the enzyme lysozyme, the aggregation of which is involved in hereditary systemic amyloidosis, single point mutations in the lysozyme gene are associated with fibril deposition in several tissues." (PMID 16302961, 2005). "It is well known that a single-point mutation of human lysozyme, namely I56T, has been identified as the origin of hereditary systemic amyloidosis." (PMID 15904486, 2005). "Furthermore, HEWL is structurally homologous to the human lysozyme whose familial mutations are associated with lysozyme systemic amyloidosis." (PMID 26571264, 2015). "Therefore, it is very possible that the location of the mutation could be a crucial factor in the propensity for lysozyme aggregation in patients suffering from systemic amyloidosis." (PMID 27926837, 2016). "The intermediate state of human lysozyme has long been elusive to biophysical analyzes despite its direct link to hereditary systemic amyloidosis." (PMID 40557600, 2025). "From a medical point of view, the significance of folding problems has recently increased because protein aggregation has been shown to lead to a number of fatal diseases, such as lysozyme systemic amyloidosis." (PMID 27768744, 2016). "The most common forms of systemic amyloidosis, such as those caused by immunoglobulin light chains, TTR, lysozyme, and lipoproteins, are prototypic examples of instances when the sites of production and of major deposition are totally different." (PMID 25750126, 2015). "The conversion of human lysozyme into amyloid fibrils is associated with a rare but fatal hereditary form of nonneuropathic systemic amyloidosis." (PMID 27926837, 2016). "Changes in the tertiary structure of proteins and the resultant fibrillary aggregation could result in fatal heredity diseases, such as lysozyme systemic amyloidosis." (PMID 27768744, 2016). "Fibril formation by mutational variants of human lysozyme is associated with a fatal form of hereditary non-neuropathic systemic amyloidosis." (PMID 23166837, 2012).
systemic amyloidosis (continued). "We have examined different types of aggregates formed by lysozyme, a protein found as fibrillar deposits in patients with familial systemic amyloidosis, by infrared spectroscopy, transmission electron microscopy, and depolymerization experiments, and analyzed how they affect cell viability." (PMID 20624399, 2010). "In 1993, hereditary non-neuropathic systemic amyloidosis was reported to be caused by naturally occurring variants of human lysozyme that aggregated in the liver." (PMID 15904486, 2005). "Human lysozyme, consistent with this behavior, forms transiently populated intermediate states that appear to be the precursors of the amyloid fibrils associated with hereditary, nonneuropathic, systemic amyloidosis." (PMID 27926837, 2016).